ALPK2 (alpha kinase 2)
Description:
Protein kinase that recognizes phosphorylation sites in which the surrounding peptides have an alpha-helical conformation.
Synonyms: HAK
Tractability: Antibody: UniProt places it where antibodies can reach, with high confidence; its Gene Ontology location is reachable by antibodies, with medium confidence. PROTAC: ubiquitination databases record sites on it.
Gene: Protein-coding gene on chromosome 18 (58,481,247 to 58,629,091, reverse strand). Ensembl gene ENSG00000198796.
Subcellular location: Basolateral cell membrane
Subcellular location (Human Protein Atlas): Cytosol
Gene Ontology:
Molecular function: ATP binding; protein serine kinase activity; protein serine/threonine kinase activity
Biological process: cardiac muscle cell development; epicardium morphogenesis; establishment of cell polarity; heart morphogenesis; negative regulation of Wnt signaling pathway involved in heart development; regulation of apoptotic process; regulation of gene expression
Cellular component: basolateral plasma membrane
Genetic constraint (gnomAD): Loss-of-function variants: 125 observed, 168.16 expected, observed/expected ratio (o/e) 0.74, 90% interval 0.64 to 0.86. The upper end of that interval is the gene's LOEUF score, 0.86, which puts it in group 3 of 6, group 1 being the genes least tolerant of losing a copy. Missense variants: 2,353 observed, 2,718.2 expected, observed/expected ratio (o/e) 0.87, 90% interval 0.84 to 0.9. Synonymous variants: 950 observed, 1,004.4 expected, observed/expected ratio (o/e) 0.95, 90% interval 0.9 to 1.
Homologues: Orthologues: chimpanzee ALPK2 (98% identical), macaque ALPK2 (91% identical), guinea pig ALPK2 (63% identical), pig ALPK2 (63% identical), dog ALPK2 (62% identical), rabbit ALPK2 (58% identical), mouse Alpk2 (56% identical), rat Alpk2 (55% identical), zebrafish alpk2 (14% identical). Paralogues in human: ALPK1 (11% identical), HSPA12A (4% identical), HSPA12B (4% identical), EEF2K (4% identical).
Diseases named in the same sentence as ALPK2 in open-access papers:
ALPK2 is named in the same sentence as 22 diseases in open-access papers, as found by Europe PMC text mining. Sharing a sentence is not in itself a finding about the gene and the disease. The quoted sentences say what the papers report.
gastric cancer (5 papers, 2010 to 2022). A primary or metastatic malignant neoplasm involving the stomach. "ALPK2 is located in the 18q12.3-q22.2 region, a region of recurrent genomic loss in gastric cancers." (PMID 20187983, 2010). "The copy number associated underexpression in gastric cancers was validated with qRT-PCR analysis as ALPK2 showed a 2.9-fold underexpression in gastric cancers with copy number losses (g1) compared with gastric cancers with normal copy number of ALPK2 (g0)." (PMID 20187983, 2010). "Other studies found that ALPK2 is associated with the prognosis of gastric cancer." (PMID 32595416, 2020). "According to the qRT-PCR analysis there was a 2.9-fold underexpression of ALPK2 in gastric cancers with copy number losses (g1) compared with gastric cancers with normal copy number of ALPK2 (g0) (p < 0.05)." (PMID 20187983, 2010). "The kinase ALPK2 is also reported to be under-expressed in gastric cancer and may be downregulated by oncogenic KRAS." (PMID 29100308, 2017). "Surprisingly, however, the expression of ALPK2 in gastric cancers in general was 1.9-fold higher (p < 0.05) than in the nonmalignant gastric tissues." (PMID 20187983, 2010).
ovarian carcinoma (4 papers, 2020 to 2024). A malignant neoplasm originating from the surface ovarian epithelium. "Furthermore, a comprehensive sequencing aiming to identify somatic mutations in potentially oncogenic kinases revealed ALPK2, as one of the mutated genes in human cancers such as ovarian cancer." (PMID 34210956, 2021). "In mouse xenograft models, the knockdown of ALPK2 inhibits the development and progression of ovarian cancer and renal cancer cells, thus supporting its relevance not only in cancer initiation and development but also in the pathogenesis of liver disease." (PMID 38540416, 2024). "To exemplify the power of NeDRex to extract biologically meaningful pathways from starting seeds, we used the ovarian cancer (OC) associated genes from NeDRexDB (AKT1, ALPK2, CDH1, CTNNB1, EPHB1, OPCML, PIK3CA, PRKN) and constructed disease module using the MuST algorithm." (PMID 34824199, 2021).
bladder cancer (3 papers, 2021 to 2024). "Our results showed the upregulation of ALPK2 in bladder cancer, and data mining of TCGA database showed the association between ALPK2 and pathological parameters of patients with bladder cancer." (PMID 34210956, 2021). "It has known that the upregulation of ALPK2 is related to the progression of bladder cancer and renal cancer." (PMID 36158685, 2022). "In this study, ALPK2 is recognized to be abundantly expressed in bladder cancer, whose expression is higher in bladder cancer tissues than normal tissues." (PMID 34210956, 2021). "In this study, we first investigated the expression levels of ALPK2 in human bladder cancer tissues and then compared these levels with those of normal tissues." (PMID 34210956, 2021). "In summary, DEPDC1A exhibited similar regulatory effects on the development of bladder cancer as ALPK2." (PMID 34210956, 2021). "This study investigated the role of ALPK2, which is rarely studied in malignant tumors, in the development of bladder cancer." (PMID 34210956, 2021). "In this study, it was found that the expression of ALPK2 in bladder cancer tissues was generally higher than that in normal tissues, indicating its potential role as a tumor promotor in bladder cancer." (PMID 34210956, 2021). "In summary, these in vitro studies clearly showed that ALPK2 plays an important role in the development and progression of bladder cancer." (PMID 34210956, 2021). "Subsequent in vitro experiments validated the role of ALPK2 in bladder cancer via uncovering the inhibition of cell proliferation and cell motility, and the promotion of cell apoptosis induced by ALPK2 knockdown." (PMID 34210956, 2021). "Collectively, these experimental results revealed the potential stimulatory role played by ALPK2 in the development and progression of bladder cancer." (PMID 34210956, 2021). "We also used qPCR and western blot to detect the endogenous expression of ALPK2 in various bladder cancer cell lines." (PMID 34210956, 2021). "Next, we demonstrated that bladder cancer cells exhibiting downregulated expression levels of ALPK2 (shALPK2) also showed significantly slower proliferation rates than the shCtrl group (P < 0.05)." (PMID 34210956, 2021). "Collectively, these results strongly confirmed the role of ALPK2 in the development and progression of bladder cancer, both in vitro and in vivo." (PMID 34210956, 2021). "In conclusion, our study revealed that ALPK2 possessed the ability of promoting development and progression of bladder cancer through the regulation of oncoprotein DEPDC1A." (PMID 34210956, 2021). "Interestingly, this gene is upregulated in human bladder cancer and knocking down ALPK2 in a mouse xenograft model of bladder cancer suppressed tumor growth." (PMID 39411517, 2024). "Additionally, DEPDC1A is identified as a potential downstream of ALPK2 with direct interaction, whose overexpression/downregulation can inhibit/promote the malignant behavioral of bladder cancer cells." (PMID 34210956, 2021). "Collectively, these results clearly demonstrated the promotion effects of ALPK2 on bladder cancer, and that DEPDC1A may also be involved." (PMID 34210956, 2021). "Notably, overexpression of DEPDC1A can interfere with the inhibitory effects of ALPK2 knockdown on bladder cancer." (PMID 34210956, 2021). "IHC analysis showed that the expression levels of ALPK2 in tumor tissues were much higher than those in normal tissues, thus indicating that ALPK2 may be involved in the development and progression of bladder cancer." (PMID 34210956, 2021). "Additionally, DEPDC1A is identified as a potential downstream of ALPK2, whose overexpression/downregulation can inhibit/promote the malignant behavioral of bladder cancer cells." (PMID 34210956, 2021). "Moreover, the overexpression of DEPDC1A can rescue the inhibitory effects of ALPK2 knockdown on bladder cancer." (PMID 34210956, 2021).
bladder cancer (continued). "Given the evident role of ALPK2 in the development of bladder cancer, we next explored the downstream mechanisms that might be responsible for its regulatory effects on bladder cancer." (PMID 34210956, 2021). "In vitro and in vivo experiments demonstrated that knockdown of ALPK2 could inhibit bladder cancer development through regulating cell proliferation, cell apoptosis, and cell migration." (PMID 34210956, 2021). "In addition, knockdown of ALPK2 can inhibit the development of bladder cancer in vivo and in vitro." (PMID 34210956, 2021). "However, the role in the development and progression of bladder cancer played by ALPK2 is rarely reported and still largely unknown till now." (PMID 34210956, 2021). "Therefore, ALPK2 may act as a tumor promotor in bladder cancer, and could be used as a potential therapeutic target in the treatment of bladder cancer." (PMID 34210956, 2021). "Next, we constructed EJ and T24 cells that overexpressed DEPDC1A, and cells in which ALPK2 was knocked down while DEPDC1A was overexpressed, and used these groups of cells to investigate the synergistic effects of DEPDC1A and ALPK2 on bladder cancer." (PMID 34210956, 2021). "All of the bladder cancer cell lines tested (EJ, T24, J82, and RT4) showed expression levels of ALPK2, although there were differences in these expression levels across different cell lines." (PMID 34210956, 2021). "In order to explore the role played by ALPK2 in the development and progression of bladder cancer, we prepared lentiviral constructs expressing shRNAs targeting ALPK2 (shALPK2-1 and shALPK2-2) or shCtrl (as a negative control); these constructs were then used to transfect EJ and T24 cells." (PMID 34210956, 2021). "In conclusion, ALPK2 exerts a cancer-promoting role in the development of bladder cancer by regulating DEPDC1A, which may become a promising target to improve the treatment strategy of bladder cancer." (PMID 34210956, 2021). "Therefore, ALPK2 exerts a cancer-promoting role in the development of bladder cancer by regulating DEPDC1A, which may become a promising target to improve the treatment strategy of bladder cancer." (PMID 34210956, 2021). "In this study, combining the bioinformatics of gene expression profiling of bladder cancer cells with or without ALPK2 knockdown and its known role in bladder cancer, DEPDC1A was identified as a potential target of the ALPK2 induced regulation of bladder cancer." (PMID 34210956, 2021).
renal carcinoma (3 papers, 2022 to 2025). A carcinoma arising from the epithelium of the renal parenchyma or the renal pelvis. "Least supported in literature is the relatively uncharacterized ALPK3, with only its paralog, ALPK2, indicated as a tumor promotor in renal cancer." (PMID 41188181, 2025).
colorectal cancer (2 papers, 2018 to 2021). A primary or metastatic malignant neoplasm that affects the colon or rectum. "ALPK2 is associated with luminal apoptosis in colorectal cancer cell lines." (PMID 33705408, 2021). "Interestingly, ALPK2 has been shown to upregulate DNA repair genes and to enable caspase-3 cleavage and apoptosis in a colorectal cancer model." (PMID 29737278, 2018).
liver disease (2 papers, 2021 to 2024). "Although warranting replication, ALPK2 rs3809973 may show utility to detect individuals at increased risk for liver disease progression." (PMID 33705408, 2021).
liver fibrosis (2 papers, 2021 to 2024). "Although the association of ALPK2 rs3809973 with fibrosis in the setting of HIV/HCV coinfection warrants replication, some circumstantial evidence suggests a potential role for ALPK2 in risk for viral hepatic fibrosis." (PMID 33705408, 2021). "In order to see if the ALPK2 variant’s tentative association with increased liver fibrosis in coinfected women was preferentially impacted by the effects of either virus, we analyzed each genotype of the ALPK2 variant across all viral serostatuses utilized in the cohort." (PMID 33705408, 2021). "Our comparisons of ALPK2 rs3809973 among serogroups at baseline therefore leads us to speculate that the risk allele’s impact on liver fibrosis is reliant on both HCV-mediated liver damage and its perpetuation by HIV-mediated immunosuppression." (PMID 33705408, 2021). "As elevations in viral HIV titers have been correlated with increased liver injury in the coinfected, our findings suggest that the genetic risk of hepatic fibrosis among coinfected individuals carrying the ALPK2 rs3809973 risk allele is not confounded by these titers." (PMID 33705408, 2021). "Therefore, we speculate that ALPK2 rs3809973 could enhance liver fibrosis by interfering with enteric immunity." (PMID 33705408, 2021). "The lack of association in coinfected participants between the ALPK2 variant heterozygote and increased liver fibrosis suggested the need for variant homozygosity for the detrimental impacts of the variant to manifest in the coinfected and conforms with a recessive mode of inheritance." (PMID 33705408, 2021).
Crohn disease (1 paper, 2024). A gastrointestinal disorder characterized by chronic inflammation involving all layers of the intestinal wall, noncaseating granulomas affecting the intestinal wall and regional lymph nodes, and transmural fibrosis. "However, ALPK2, over-expressed in human IBD and mostly in ulcerative colitis, was equally expressed in Maffl/flCd4Cre and double-deficient Prdm1fl/fMaffl/fCd4Cre mice, while CXCL10 was increased in both ulcerative colitis and Crohn’s disease, and was highest in the double-deficient LPLs." (PMID 38609547, 2024).
endometrial carcinoma (1 paper, 2022). A malignant tumor arising from the epithelium that lines the cavity of the uterine body. "Immunohistochemistry revealed ISH scores for four risk kinases (ALPK2, TTK, PTK6, and CIT) were significantly higher in endometrial carcinoma tissues than in healthy endometrium, which suggested that high expression of these genes may contribute to the progression of UCEC." (PMID 36158685, 2022). "Using univariate Cox regression and Least absolute shrinkage and selection operator (LASSO), seven kinases (ALPK2, CAMKV, TTK, PTK6, MAST1, CIT, and FAM198B) were identified to establish a prognostic model of endometrial cancer." (PMID 36158685, 2022).
inflammatory bowel disease (1 paper, 2021). A spectrum of small and large bowel inflammatory diseases of unknown etiology. "In addition, a genome-wide association study of inflammatory bowel disease, a condition in which pathological epithelial shedding is observed, found the mRNA of ALPK2 to be up-regulated in inflamed mucosa compared to control samples." (PMID 33705408, 2021).
liver cancer (1 paper, 2024). An epithelial or non-epithelial malignant neoplasm that arises from the liver. "To identify the biological pathways associated with ALPK2, we performed gene set enrichment analysis (GSEA) using a TCGA liver cancer patient cohort from the cBioPortal database." (PMID 38540416, 2024).
cancer (10 papers, 2016 to 2024). A tumor composed of atypical neoplastic, often pleomorphic cells that invade other tissues. "Although the biological function of ALPK2 and its role in malignant tumor has been studied to some extent, the understanding of ALPK2 is still far from enough." (PMID 34210956, 2021). "Alpha protein kinase 2 (ALPK2) was known to play a vital role in cancer by regulating cell cycle and DNA repair." (PMID 32595416, 2020). "ALPK2 (Alpha Kinase 2) is a member of an atypical alpha protein kinase family and could regulate cell cycle and DNA repair genes to participate in cancer development." (PMID 36158685, 2022). "ALPK2 is essential in cancer as it regulates the cell cycle and DNA repair genes." (PMID 34966691, 2021). "In addition, ALPK2 has been reported to be essential in cancer by regulating cell cycle and DNA repair genes." (PMID 32595416, 2020). "At present, research on the mechanism of ALPK2 in cancer is still scarce." (PMID 32595416, 2020).
tumor (9 papers, 2010 to 2025). "In order to further investigate the influence of ALPK2 knockdown on tumor growth in vivo, we constructed mice xenograft models via the subcutaneous injection of T24 cells transfected with either shALPK2 (shALPK2-1) or shCtrl." (PMID 34210956, 2021). "The F72 and F75 tumors shared genes mediating inflammation and angiogenesis, whereas ALK and ALPK2 kinases were specifically expressed in each tumor, respectively." (PMID 33853673, 2021). "In addition, ALPK2-induced inhibition of tumor growth was also supported by the lower Ki67 in tumors formed by T24 cells transfected with shALPK2, as well as the downregulation of ALPK2 in shALPK2 xenografts." (PMID 34210956, 2021). "It was also found that ALPK2 knockdown inhibited tumor growth in xenograft mice in vivo." (PMID 32595416, 2020). "Firstly, tumor and normal tissues were collected for detecting expression of ALPK2 in OC." (PMID 32595416, 2020). "Moreover, the mutations ALPK2.R136S, CHST9.S122N, FAM38B.V2463, LAMA1.S1577A, LAMA1.K2002E, MYOM1.T215M, SERPINB10.R246C and SLC14A2.A880T were found in all three tumor samples and shared a similar frequency profile." (PMID 23892400, 2013). "No previous publications regarding the possible tumor association of ALPK2 or its function in normal tissues have been published." (PMID 20187983, 2010). "Moreover, we have uncovered new genes affected by frameshift MSI events in MSI-prone tumours as well as in tumour types not frequently affected by MSI (for example, FAM129A, GMIP and NEK3 in BRCA, and DPYSL2 and ALPK2 in OV)." (PMID 28585546, 2017).
ALPK2 also shares sentences with these, for which no sentence is quoted: adenoma (1 paper); breast carcinoma (1); melanoma (1); non-small cell lung carcinoma (1); Obesity (1); osteosarcoma (1); ovarian serous cystadenocarcinoma (1); periodontitis (1); ulcerative colitis (1).